CTCF (CCCTC-binding factor)
Diseases named in the same sentence as CTCF in open-access papers (continued):
Sharing a sentence is not in itself a finding about the gene and the disease.
cancer (continued). "Of note, DNA-binding motif of the CTCF protein in loop anchor regions is one of the most frequently altered TF-binding sequences in human cancer." (PMID 34761120, 2021). "As CTCF exhibits haploinsufficiency in cancer, the interplay between mutant and wildtype CTCF at specific loci and at target sites genome-wide remains an unanswered question." (PMID 34657170, 2021). "Pathway analysis of the candidate DEGs showed that the genes are mostly involved in the CTCF and Wnt signaling pathways (BioCarta), as well as pathways in cancer and Wnt signaling pathways (KEGG)." (PMID 34959833, 2021). "To demonstrate the applicability of the RCRA ChIP-seq procedure to other cancer types in different hospitals, we mapped the active chromatin marks H3K4me3 and H3K27ac, and binding sites of CTCF in OCCC samples." (PMID 33924956, 2021). "This suggests that the ability of stress signals to modulate the abundance and function of a certain pool of CTCF is deregulated in the cancer cell lines that we tested." (PMID 33411704, 2021). "Here, we introduce svMIL2, an improved version of our Multiple Instance Learning-based method to study the effect of somatic non-coding SVs disrupting boundaries of TADs and CTCF loops in 1646 cancer genomes." (PMID 34257393, 2021). "Most of our information about CTCF biology is based on studies using cancer cell lines, embryonic stem cells or fibroblasts under unstressed conditions." (PMID 33411704, 2021). "Our research clarified a new functional element that recruits CTCF and collaborates with histone deacetylation to maintain high-order chromatin organizations, linking to long-range gene regulation in cancer genomes." (PMID 35127534, 2021). "Conversely, S100A8/A9 binding decreases at CTCF motifs during transformation, and CTCF haploinsufficiency in mice leads to increased cancer incidence." (PMID 33523865, 2021). "In cancer cells, CTCF can also undergo a number of post-translational modifications which change its properties and functions." (PMID 35011637, 2021). "One study showed that upon genotoxic damage in cancer cell lines, CTCF is rapidly recruited to DNA damage sites via interaction of zinc finger DNA binding motifs with poly (ADP-ribose) (PAR) moieties." (PMID 33411704, 2021). "In cancer, genetic alteration or hypermethylation of CTCF sites at TAD boundaries can disrupt chromatin topology and lead to aberrant activation of oncogenes." (PMID 34657170, 2021). "For example, RNAi-mediated downregulation of CTCF in certain cancer cell lines results in destabilization of chromatin boundary elements and aberrant epigenetic silencing of specific tumor suppressor genes." (PMID 33411704, 2021). "In the human cancer cell lines that we examined, CTCF protein levels were quite variable depending upon the cell line and levels were not affected by stress." (PMID 33411704, 2021). "Understanding the functional crosstalks between CTCF and other HR factors will illuminate the molecular basis of various human diseases that range from developmental disorders to cancer and arise from impaired repair." (PMID 33673494, 2021). "One such modification which has been linked to cancer is poly (ADP)-ribosylation (PARylation) at the n-terminal domains of CTCF, which promote the insulator and transcription factor functions of CTCF, while phosphorylation impairs its DNA binding activity." (PMID 35011637, 2021). "Its specialized paralog, BORIS, heterodimerizes with CTCF but is expressed only in male germ cells and in cancer states." (PMID 34158481, 2021). "Studies have revealed that CTCF is robustly upregulated in several cancers and promotes the malignant characteristics of tumor cells." (PMID 32688344, 2020). "In the current work, a query of human cancer samples highlights the frequency (27% PCa; 62% BCa) of CTCF copy number alteration in primary tumors." (PMID 32503656, 2020).
cancer (continued). "To better understand the prognostic power of CTCF, we performed further subset analyses in cancers with identical classical and quantitative Gleason scores." (PMID 31736271, 2020). "These cancers have CTCF ChIP-seq data available in both cell lines and corresponding normal tissues." (PMID 32933554, 2020). "In a similar vein, super-enhancers control human MYC transcription via CTCF in the context of high-MYC cancers." (PMID 32527935, 2020). "Despite this characterization, the extent and contribution of CTCF expression in cancer development is not well understood." (PMID 32503656, 2020). "Cancer cells show increased allele switching at ASM loci, but disruptive SNPs in specific classes of CTCF and transcription factor binding motifs are similarly correlated with ASM in cancer and non-cancer." (PMID 32594908, 2020). "CTCF, EP300 and LMO2 are listed in the Catalog Of Somatic Mutations In Cancer (COSMIC) as genes that are causally implicated in cancer if mutated." (PMID 32850701, 2020). "While our observations of cancer-specific lost CTCF sites are consistent with this “enhancer docking” model, further studies are required to understand the causal relationships between CTCF binding loss and gene repression." (PMID 32933554, 2020). "Cancer-specific CTCF recruitment likely results from other TFs that indirectly open chromatin and alter chromatin conformation." (PMID 32933554, 2020). "To investigate if the persistent CTCF sites identified in the cancer LNCaP cells were also persistent in an unrelated cell type we performed CTCF knockdown in normal IMR90 cells and achieved ~80% knockdown of CTCF mRNA." (PMID 31911579, 2020). "Collectively, these data suggest epigenetic deregulation by altered CTCF is a crucial mediator of cancer formation and progression." (PMID 32503656, 2020). "Our analyses focused on several key NMPs including SATB1/2, SAFB1/2, EZH2, SUZ12, BMI1, PCL3, RAE28, and CTCF, as these NMPs have been shown to be aberrantly expressed in cancers." (PMID 33124191, 2020). "ASM is increased in cancers but occurs by a shared mechanism involving disruptive SNPs in CTCF and transcription factor binding sites in both normal and neoplastic cells." (PMID 32594908, 2020). "The contributions of chromatin insulation in cancer development can be further explored via modulation of DNA methylation on CTCF-bound insulator using dCas9-DNMT3a (DNA methylase) or dCas9-TET1 (DNA demethylase)." (PMID 32941624, 2020). "That CTCF lacks prognostic impact in cancers with identical (classical and quantitative) Gleason is another proof for the unprecedented prognostic power of Gleason scoring when it is performed in a specialized center." (PMID 31736271, 2020). "Particularly, high CTCF expression was significantly associated with the presence of the transmembrane protease, serine 2:ETS‐related gene fusion: Only 10% of ERG‐negative cancers, but 30% of ERG‐positive cancers had high‐level CTCF expression (P < 0.0001)." (PMID 31736271, 2020). "To resolve this issue, we performed chromatin immunoprecipitation-sequencing (ChIP-seq) analysis of CTCF and cohesin binding in several cancer cell lines." (PMID 31937660, 2020). "Given the ubiquitous nature of CTCF binding throughout the genome, these data strongly suggest CTCF is important in dictating the cancer-specific DNA methylation landscape." (PMID 32503656, 2020). "What role does CTCFL play in regulating chromatin organization and gene expression in a cancer setting where it is expressed in the presence of CTCF?" (PMID 32393311, 2020).
cancer (continued). "Data on ERG expression obtained by IHC and on transmembrane protease, serine 2:ETS‐related gene fusion (TMPRSS2:ERG) rearrangement obtained by FISH were available from 7935 and from 5360 cancers with interpretable CTCF staining results." (PMID 31736271, 2020). "In cancers, detectable nuclear CTCF staining was seen in 7726 of our 12 555 (61.5%) tumors and was considered low in 44.6% and high in 17% of cancers." (PMID 31736271, 2020). "In the non‐coding cancer genome, CCCTC binding factor (CTCF)/cohesin's binding sites (CBSs) are major mutational hotspots." (PMID 32865336, 2020). "We compared both CTCF occupancy frequencies and normalized CTCF binding levels in samples from each cancer type versus all other samples as well as their corresponding normal tissue to account for variations due to sample specificity." (PMID 32933554, 2020). "Specifically, we investigate the enrichment of somatic mutation, abnormal methylation, and copy number alteration events in the proximity of CTCF bindings overlapping with topological boundaries (junctions) in 26 cancer types." (PMID 31945090, 2020). "CTCF is a well-known transcription factor that is essential in organizing chromatin and regulates target genes related to cancer." (PMID 33665169, 2020). "Previous study suggested that CTCF is a tumor suppressor and it can regulate the expression of various cancer-related genes." (PMID 30886832, 2019). "The therapy approach of targeting CTCF seems to be promising for the treatment of PC by regulating the FoxO signalling pathway and further retarding cancer progression." (PMID 30873749, 2019). "This evidence provides support for the germane role of CTCF in the regulation of epigenetic effects of tumor suppressor genes and cancer development." (PMID 31852961, 2019). "In this regard, BORIS (CTCFL), a CTCF paralog, is a promising cancer biomarker that is overexpressed and controls transcription in several cancer types, mainly in OC." (PMID 31406110, 2019). "The cell model and results collected from this study will expedite the investigation of CTCF’s impact on transcriptional regulation in cancers and other biological processes." (PMID 31127282, 2019). "Such nucleolar localization of a protein involved in transcriptional regulation and gene repression in cancer cells was observed with CCCTC-binding factor (CTCF)." (PMID 29716651, 2018). "Our study clearly demonstrates that CTCF is a haploinsufficient tumour suppressor gene that is essential for somatic cell viability and protects against cancer." (PMID 30513694, 2018). "One interesting member of the cancer testis gene family is BORIS/CTCFL, which encodes a homologue of the insulator protein CCCTC binding factor (CTCF)." (PMID 29649096, 2018). "In the majority of telomerase-positive cells such as cancer cell lines and tumors, hypermethylation of hTERT exon 1 region prevents the binding and prevents the repressive effects of CTCF." (PMID 30323717, 2018). "The fact that tapRNAs overlap CTCF and ZNF263 motifs that are mutated in cancer also points to genomic organization as an important node in homeostasis and disease." (PMID 29540241, 2018). "Expression of BORIS in cancer cells likely leads to its interference with CTCF function by competition for binding to CTCF DNA binding target sites." (PMID 30323717, 2018).
cancer (continued). "Another non-mutually exclusive possibility is that BORIS interacts with an alternative, cancer-testis specific set of architectural factors which are normally co-expressed together with CTCF and BORIS only during gametogenesis." (PMID 29077515, 2018). "This, in turn, can induce tumour suppressor silencing; disruption of CTCF-dependent insulation leading to aberrant TAD formation and oncogene activation; and cis-activation of genes implicated in cancer." (PMID 30513694, 2018). "We and others have found that the mechanism of CTCF gene inactivation differs between cancer subtypes." (PMID 28319062, 2017). "Such cancer type–specific associations were also seen for PIK3CA, KRAS, GATA3, CTCF, CDH1, and ARIDA1." (PMID 29125844, 2017). "Other studies also revealed that ~ 20–30% of cohesin sites in different human cancer cell lines and up to ~ 50% of cohesin sites in mouse liver appear to be CTCF-free." (PMID 28855971, 2017). "Some studies have reported that CTCF can slow cell cycle progression, disrupt cell division and inhibit cell growth by regulating various growth-related genes in multiple types of cancers." (PMID 28977939, 2017). "By contrast, CTCF overexpression markedly reduced the migration and invasion of cancer cells in vitro and tumorigenicity in vivo." (PMID 29212169, 2017). "CCCTC-binding factor (CTCF) functions as both an oncogenic and a tumor suppressor, depending on the cancer type, through epigenetic regulation." (PMID 28977939, 2017). "The differentially methylated region (DMR) in the imprinted H19 locus contains two CTCF target sites that, in many cancer cells, are both hypermethylated and incapable of binding CTCF." (PMID 28587163, 2017). "Future studies to explore the global consequences of CTCF haploinsufficiency on three-dimensional genomic architecture and the transcriptional landscape in cancer are now warranted." (PMID 28319062, 2017). "We investigated the metabolic and mechanistic processes that regulate PARP-1-mediated CTCF PARylation in human cancer cell lines and discovered a key role for the expression and activity of β-NAD+ salvage enzymes, NAMPT and NMNAT-1." (PMID 29029387, 2017). "Thus, CTCF sites involved in higher order chromatin structures appear to suffer the highest mutational burden, and chromatin organization may be affected by this increased mutational input across several cancer types." (PMID 27490693, 2016). "The germline-specific transcription factor BORIS/CTCFL, a paralog of chromatin architecture protein CTCF, is often erroneously activated in cancers and rewires the epigenome for the germline-like transcription program." (PMID 27588042, 2016). "The simultaneous binding of BORIS and CTCF genome-wide in cancer cell lines was shown to reset, at least partially, the functions of CTSs in transcriptional regulation in accordance with germline-like program." (PMID 27588042, 2016). "The tissue-specific expression of GnT-IX is regulated by the specific transcription factors NeuroD1 and CCCTC-binding factor (CTCF) but their contributions to the cancer-related upregulation of GnT-IX are still unclear." (PMID 27136596, 2016). "CTCF elements that demarcate TAD boundaries are commonly disrupted in cancer and promote oncogene activation." (PMID 27669308, 2016). "We used mainly the established cancer cell line K562 as a model for the coexistence of CTCF and BORIS stably expressed at a relatively the same level, as assayed by RT-PCR, to assess genome repeat occupancy by these two proteins." (PMID 27588042, 2016). "In this study, we established that BORIS, upon its activation at a relatively high level in cancer cells, has a substantial capacity to occupy the same sites in the repeated elements as CTCF." (PMID 27588042, 2016). "For example, the testis-specific promoter of the GAL3ST1 gene was silenced when occupied by CTCF alone in most BORIS-negative cell lines, but it was activated in BORIS-positive cells (germ and cancer) when co-occupied by CTCF and BORIS." (PMID 26268681, 2015).
cancer (continued). "The originally proposed model for BORIS’ “invasion” of CTSes upon its expression in germline and cancers was that BORIS simply outcompetes CTCF for binding at some sites." (PMID 26268681, 2015). "Further, results from EMSA, ChIP-Re-ChIP, co-immunoprecipitation, and ISPLA in both cancer and germ cells support the co-occupancy of 2xCTSes by CTCF and BORIS." (PMID 26268681, 2015). "The patterns of BORIS and CTCF occupancy were very similar among the three cancer cell lines despite their distinct tissue origins." (PMID 26268681, 2015). "In contrast to the single-motif CTCF target sites (1xCTSes), the 2xCTS elements are preferentially found at active promoters and enhancers, both in cancer and germ cells." (PMID 26268681, 2015). "In cancer, methylation negatively affects the interaction between CTCF and the XAF1 promoter, disabling the protective epigenetic actions of CTCF against the closed-chromatin configuration." (PMID 26443201, 2015). "In cancer, CTCF is thought to be a tumor suppressor, while CTCFL/BORIS has been suggested as an oncogene." (PMID 24658009, 2014). "Global DNA hypomethylation was evident in both MCF7 and PC3 cancer cells surrounding CTCF and fCTCF sites as well as the NDRs and DNase I sites." (PMID 24916973, 2014). "We again observed fewer DNase I hypersensitive sites overlapping enhancers and a greater number of DNase I sites overlapping CTCF sites in cancer cells, supporting the NOMe-seq results." (PMID 24916973, 2014). "Categorization of the epigenome into ChromHMM states showed that NDRs are predisposed to overlap enhancers in normal cells; however, we found that NDRs preferentially overlapped CTCF sites in cancer cells." (PMID 24916973, 2014). "Together, these data support our finding that fewer NDRs overlap enhancers in cancer cells and is also consistent with our observation that a greater number of CTCF sites overlap a NDR in cancer cells." (PMID 24916973, 2014). "BORIS has been shown to become deregulated in cancers, and to compete with CTCF for binding occupancy." (PMID 23745176, 2013). "Recent studies have shown that CTCF is also involved in the regulation of miRNAs such as miR-125b1, miR-375, and the miR-290 cluster in cancer cells and stem cells." (PMID 23056006, 2012). "CTCF is ubiquitous in normal tissues, has cell growth restrictive activities and is often lost in cancer." (PMID 22724006, 2012). "The involvement of CTCF in cancer and in particular, in the epigenetic regulation of tumor suppressor genes, is further supported by recent data from other laboratories studying the BRCA1 and p16INK4a tumor suppressor genes, or even the apoptotic gene PUMA." (PMID 21663659, 2011). "CTCFL or BORIS (Brother of the Regulator of Imprinted Sites), a paralog of CTCF, has been classified as a cancer-testis antigen as its distribution is reported to be limited to the testis and certain cancers." (PMID 21811597, 2011). "On the basis of the data accumulated by our group and other laboratories, it is now critical to begin addressing mechanistic questions concerning the aberrant performance of CTCF in cancer cells." (PMID 21663659, 2011). "It has been suggested that the expression of BORIS displaces CTCF in the genome and leads to proliferation of cancer cells." (PMID 22168535, 2011). "In conclusion, although molecular functions of BORIS in cancer remain to be studied in depth, aberrant co-expression of CTCF and BORIS is one of the gene expression signatures characteristic of many cancers." (PMID 21079786, 2010). "This region binds the transcriptional repressor CTCF and in cancer cells CTCF repression was shown to be relieved by methylation of its binding site." (PMID 20534141, 2010).